GPT (glutamic--pyruvic transaminase)
Description:
Catalyzes the reversible transamination between alanine and 2-oxoglutarate to form pyruvate and glutamate. Participates in cellular nitrogen metabolism and also in liver gluconeogenesis starting with precursors transported from skeletal muscles (By similarity).
Synonyms: ALT1; AAT1; GPT1; ALT; SGPT
Tractability: PROTAC: its protein half-life has been measured.
Target class: Enzyme; Transferase
Gene: Protein-coding gene on chromosome 8 (144,502,608 to 144,507,494, forward strand). Ensembl gene ENSG00000167701.
Subcellular location: Cytoplasm
Pathways (Reactome):
Metabolism: Alanine metabolism; Pyruvate metabolism
Gene Ontology:
Molecular function: L-alanine:2-oxoglutarate aminotransferase activity; pyridoxal phosphate binding; transaminase activity
Biological process: L-alanine catabolic process
Cellular component: extracellular exosome; cytosol; cytoplasm; extracellular region
Genetic constraint (gnomAD): Loss-of-function variants: 62 observed, 47.87 expected, observed/expected ratio (o/e) 1.3, 90% interval 1.05 to 1.6. The synonymous counts are far from expectation, so gnomAD's model fits this gene poorly and the ratio says little. Missense variants: 853 observed, 686.13 expected, observed/expected ratio (o/e) 1.24, 90% interval 1.17 to 1.32. Synonymous variants: 397 observed, 295.18 expected, observed/expected ratio (o/e) 1.34, 90% interval 1.24 to 1.46.
Homologues: Orthologues: chimpanzee GPT (99% identical), macaque GPT (97% identical), guinea pig GPT (91% identical), mouse Gpt (87% identical), tropical clawed frog gpt (71% identical), zebrafish gpt (69% identical), zebrafish GPT (68% identical), Caenorhabditis elegans C32F10.8 (55% identical), Drosophila melanogaster CG1640 (52% identical), Caenorhabditis elegans nkat-3 (15% identical), Caenorhabditis elegans nkat-1 (15% identical). Paralogues in human: GPT2 (67% identical), TAT (21% identical), KYAT1 (18% identical), ACCS (17% identical), ACCSL (17% identical), KYAT3 (16% identical), AADAT (14% identical).
Diseases named in the same sentence as GPT in open-access papers:
GPT is named in the same sentence as 1,111 diseases in open-access papers, as found by Europe PMC text mining. Sharing a sentence is not in itself a finding about the gene and the disease. The quoted sentences say what the papers report.
diabetes (1,679 papers, 2005 to 2026). "Elevated glutamate-pyruvate transaminase (GPT) values in fatty liver disease is significantly associated with diabetes and is a useful first indicator of glucose metabolism disturbance." (PMID 35154608, 2021). "The rise in GPT and GOT has been significantly associated with pre-diabetes and diabetes, making them very useful first indicators of disturbed glucose metabolism." (PMID 36364861, 2022). "improved symptoms of hyperglycemia and blunted the increases in serum GOT/GPT levels in a rat model of streptozotocin-induced diabetes." (PMID 28348624, 2017). "According to a previous study, high levels of glutamic-pyruvic transaminase (GPT) can increase the risk of diabetes, and the effects are independent of obesity or high triglyceride levels." (PMID 35810252, 2022). "In contrast, in a study of the Japanese population, neither GOT nor GPT was associated with diabetes risk." (PMID 35740093, 2022). "The activity of transaminases in gluconeogenesis and ketogenesis in diabetes like glutamate pyruvate transaminase (GPT) in serum and glutathione peroxidase in cytosolic liver returned to normal levels after the administration of ethanolic leaf extract in diabetic rats." (PMID 24511547, 2014). "Other contributing factors were diabetes mellitus, dense ACM sign on CT, older age, obesity, early neurological deterioration, QT interval, and elevated GOT and GPT levels, as well as lower LDL cholesterol, total cholesterol, and triglycerides." (PMID 40283013, 2025). "Even after controlling for related confounding variables, including sex, smoking and drinking status, diabetes mellitus, heart rate, TBA, GPT, GOT, TC, LDL, serum UA, and urine UA, a high level of NVAI was still a risk factor for SRD." (PMID 37029402, 2023). "GCG, IRS1, VEGFA, STAT3, CCL2, CASP3, and APOE as diabetes mellitus-related proteins and SREBF1, LPL, PPARA, APOB, GPT, MAPK8, and FASN as NAFLD-specific proteins were identified as possible discriminating factors between the two studied diseases." (PMID 35154608, 2021). "Moreover, we find CRP, GGT1, GPT, and GDF15 to be highly enriched for multiple disease terms related to cardiovascular diseases and diabetes in the GLAD4U disease database." (PMID 37590326, 2023). "Meanwhile, phycocyanin also significantly decreased the diabetes-induced abnormal serum biomarker variations, including triglyceride (TG), total cholesterol (TC), aspartate transaminase (AST), and glutamic-pyruvic transaminase (ALT), and increased the superoxide dismutase (SOD) content." (PMID 37430932, 2022).
Hepatic steatosis (1,447 papers, 2003 to 2026). Steatosis is a term used to denote lipid accumulation within hepatocytes. "Elevated GGT and GPT–values as well as estimates of fatty liver disease are significantly associated with pre-diabetes and diabetes and thus very useful first indicators of a disturbed glucose metabolism." (PMID 21850244, 2011). "In conclusion elevated GGT and GPT – values as well as estimates of fatty liver disease are significantly associated with pre-diabetes and diabetes and thus easily available and relatively inexpensive first indicators of a disturbed glucose metabolism." (PMID 21850244, 2011). "In an animal model, HFD-fed LysMCre-RORαfl/fl illustrated a lower level of M2 markers in RORα-deficient KCs, and resulted in severe hepatic steatosis, increment in serum glutamic pyruvic transaminase (GPT) and glutamic oxaloacetate transaminase (GOT), and hepatocyte ballooning with lipid droplets." (PMID 30060570, 2018). "DMF was also able to prevent or reverse the development of cellular hypertrophy in adipose tissues and the ectopic deposition of lipids in the liver, a typical feature of hepatic steatosis concomitant with a reduction in GPT levels, a marker of liver injury." (PMID 39765824, 2024). "In the odds ratio comparison between the four different fatty liver subgroups, obese, high FBG, metabolic syndrome, and high GPT showed a salient trend (p < 0.001); the data increased along with the severity of fatty liver." (PMID 38004157, 2023). "Workers who had mild, moderate, or severe fatty liver also showed an increased likelihood of having high GPT levels (with odds ratios of 2.3, 8.4, and 28.3, respectively) compared to those without fatty liver." (PMID 38004157, 2023). "Furthermore, a notable rise in the count of GOT and GPT with increased severity of fatty liver (p for linear trend < 0.001)." (PMID 38004157, 2023). "Other studies used blood tests, for example, elevated liver enzymes (e.g., Glutamic Pyruvic Transaminase GPT) as a marker of liver steatosis, but aminotransferase levels may be normal in up to 78% of patients with NAFLD." (PMID 31010049, 2019). "Furthermore, GN administration also reduced the HFD-induced hepatic triglyceride and the serum levels of GOT and GPT, indicating that GN improved hepatic steatosis and hepatic injuries in the HFD-induced obese mice." (PMID 28067305, 2017). "Moreover, the activities of GST/GOT and ALT/GPT were the most sensitive indicators of liver cell damage, which is increased by dietary MI, this indicates that the addition of MI alleviates the damage of liver cells and avoids the formation of fatty liver." (PMID 33238508, 2020). "Our results indicate that EF-2001 administration decreases liver damage by reducing the physical size of the HFD-induced fatty liver and lowering the levels of enzymes, such as GOT and GPT, released in the blood following liver damage." (PMID 36901915, 2023). "High-fat content increases the TG, AST/GOT, ALT/GPT, CHO, and LDL levels, all of which are indicators of fatty liver disease." (PMID 36457182, 2023). "Patients with fatty liver and hepatitis had higher GOT levels, while higher GPT levels were usually found in hepatic steatosis patients." (PMID 23519246, 2012).
liver disease (1,429 papers, 2005 to 2026). "Ln(ALT) activity was positively correlated with ln(AST) activity and was negatively correlated with the number of derived A GPT alleles for both clinically healthy dogs and dogs with liver disease or injury." (PMID 26683458, 2015). "AST (SGOT): Aspartate aminotransferase (Serum Glutamic-Oxaloacetic Transaminase); ALT (SGPT): Alanine transaminase (Serum Glutamic-Pyruvic Transaminase); MASLD: Metabolic dysfunctional-associated steatotic liver disease." (PMID 41561302, 2025). "In patients with AATD, gamma-glutamyl transferase is the most sensitive marker for the diagnosis of liver disease, with a mean concentration significantly higher than that of glutamic pyruvic transaminase." (PMID 39661838, 2024). "When liver disease occurs, the permeability of liver cells increases, and GPT and GOT are released into the blood, leading to increased activity of GPT and GOT in the serum." (PMID 38067056, 2023). "PN: parenteral nutrition, PNALD: parenteral nutrition-associated liver disease, GIR: glucose infusion rate, BUN: blood urea nitrogen, SBR: serum bilirubin, SGPT: serum glutamic-pyruvic transaminase." (PMID 34178539, 2021). "CO is presently manufactured and marketed as GODEX capsules or as Ganezin, by Celltrion Pharmaceutical, and it is employed for the treatment of hepatic diseases characterized by an increase of serum Glutamic Pyruvic Transaminase (sGPT) in liver tissues." (PMID 30275413, 2018). "Out of liver disease markers serum glutamic pyruvic transaminases (SGPT), serum glutamic oxaloacetic transaminases (SGOT), gamma-glutamyl transferase (GGT), and Lactic acid degydrogenase (LDH) had an inverse correlation with the advancement of the disease indicating subclinical liver disease." (PMID 32365131, 2020). "Serum glutamic oxaloacetic transaminase (SGOT) and serum glutamic pyruvic transaminase (SGPT) may be elevated secondary to both liver disease and muscle breakdown." (PMID 28524083, 2017). "Thus, it could be concluded that GPT is more useful than GOT as a specific marker for liver disease." (PMID 40868071, 2025). "The glutamic-pyruvate transaminase (GPT) and glutamic-oxalacetic transaminase (GOT) activities are positively related to the inflammatory status, especially the occurrence of liver disease." (PMID 36677779, 2023). "All included individuals exerted normal ranges of transaminases excluding chronic e.g. liver diseases, since the rages at T0 were: 15-20 U/l GGT, 22 U/l GPT and 23 U/l GOT." (PMID 34084163, 2021). "Comparison between ALS females vs. males enlightened significantly higher values in males for enzyme markers of liver disease (GOT (AST) p ≤ 0.035; GPT (ALT) p ≤ 0.014; GTP (γ-GT) p ≤ 0.038)." (PMID 28427413, 2017). "Correlation of aspartate aminotransferase (AST) activity and GPT genotype with alanine aminotransferase (ALT) activity in clinically healthy dogs and dogs with liver disease or injury." (PMID 26683458, 2015). "Low GPT enzymatic activity in the liver can be demonstrated by the fact that many birds with hepatic disorders do not show changes in serum GPT levels." (PMID 38791683, 2024). "The role of transaminases (GPT and GOT), and history of liver disease are also interesting." (PMID 38730063, 2024). "Therefore, GPT and GOT activities in serum can be used as markers to measure liver disease or damage." (PMID 37908498, 2023). "For example, variant rs112574791 from gene glutamic pyruvic transaminase (GPT), which encodes cytosolic ALT, is strongly associated with lower serum ALT levels yet not liver disease (pALT = 1.27 × 10−105, pany_liver_disease > 0.1)." (PMID 34184762, 2021). "The activities of serum enzymes GPT and GOT are sensitive indicators of liver cell injury that may help recognize hepatic diseases." (PMID 34943266, 2021).
liver disease (continued). "We found on PheWAS that genetic variants in/near the genes coding for ALT (GPT), AST (GOT1/GOT2), and ALP (ALPL) did not themselves associate with liver diseases or other diagnoses suggesting that the liver enzymes are likely not themselves pathogenic." (PMID 33547301, 2021). "Elevations of the transaminases (GOT, GPT), especially a ratio of GOT/GPT higher than 2 might be indicative of alcoholic liver disease instead of liver disease from other etiologies." (PMID 27582365, 2016). "In T2DM conditions, kidney and liver disorder is also found, which could be seen from the increase of serum blood urea nitrogen (BUN), creatinine, serum glutamic-oxaloacetic transaminase (SGOT), and serum glutamic-pyruvic transaminase (SGPT) concentration." (PMID 32399477, 2020).
Hypertension (1,247 papers, 2002 to 2026). The presence of chronic increased pressure in the systemic arterial system. "Meanwhile, in the analysis of the permutation importance method, hypertension history and serum glutamic-pyruvic-transaminase level followed the top five factors." (PMID 34070504, 2021). "Triglycerides, GPT, and ALP are the biochemical markers that changed the most in the group of hypertension patients." (PMID 34703628, 2021). "The generated risk assessment models included age, reduced left ventricular ejection fraction, reduced right ventricular function, moderate/severe tricuspid regurgitation, systolic pulmonary artery pressure, arterial hypertension, d‐dimer, CRP, PCT, TnI, LDH, GPT, and/or NT pro‐BNP." (PMID 35789499, 2022). "Compared to baseline data, age, prevalence of hypertension, systolic and diastolic blood pressures, heart rate, BMI, fasting glucose, HbA1c, serum creatinine, total cholesterol, triglyceride, GOT, and GPT were increased and uric acid and albumin were decreased at follow-up." (PMID 34357115, 2021).
liver fibrosis (1,236 papers, 1996 to 2026). "Saadati, Hatami found that only the curcumin group experienced significant reductions in hepatic fibrosis, serum cholesterol, glucose, and glutamic-pyruvic transaminase (ALT)." (PMID 36435779, 2022). "Furthermore, inhibiting autophagy could alleviate CCl4-induced liver fibrosis and the contents of serum glutamic pyruvic transaminase (ALT) and glutamic oxaloacetic transaminase (AST)." (PMID 29760379, 2018). "Glutamic-pyruvic transaminase (ALT) and glutamic oxalacetic transaminase (AST) were regards as important index for liver fibrosis or injury." (PMID 34183746, 2021). "Leukopenia, hepatic manifestations (liver fibrosis, GOT, and GPT elevations) and signs of renal disease and muscular dystrophy were also markedly improved." (PMID 31835809, 2019). "Upon our study, liver fibrosis induced by CCl4 intoxication in mice was established from significant alterations in the serum GOT, GPT and MAO levels as found by previous researchers." (PMID 23341968, 2013). "However, the serum GOT, GPT and MAO activities declined in the GA-supplemented groups, suggesting that GA protected the mice against CCl4-induced liver fibrosis to some extent." (PMID 23341968, 2013). "Also, S. tetrandra S. Moore reduced the levels of serum GOT and GPT in the rat cirrhosis model induced by CCL4, and it was effective in reducing hepatic fibrosis and nodular formation." (PMID 18475741, 1996). "Energy substances such as glucose and lactate were negatively correlated with liver function (GOT and GPT) and positively with fibrosis markers (ColIV, LN, PCIII, and HA), indicating that energy metabolism was shifted from aerobic into anaerobic respiration in liver fibrosis rats." (PMID 30210344, 2018).
steatosis (873 papers, 2005 to 2026). Increased lipid within the cytoplasm of cells. "Patients with moderate/severe steatosis had high levels of alpha-2 (%) and alpha-2, triglycerides, ferritin, cholinesterase, GPT, PTH Intact, and WBC, p < 0.05." (PMID 37242264, 2023). "We also found steatosis in the liver and markedly elevated plasma levels of GOT, GPT, TC, TG, and LDL cholesterol." (PMID 35889886, 2022). "Based on the results of elevated plasma GOT and GPT levels in mice fed the MCD diet for four weeks, we speculated that this group of mice developed severe steatosis." (PMID 35723408, 2022).
Obesity (872 papers, 2008 to 2026). Accumulation of substantial excess body fat. "According to the RNA-seq data, active beige adipocytes carrying obesity-risk genotype expressed lower mRNA level of glutamic pyruvic transaminase (GPT) 2 as compared to risk-free allele carriers." (PMID 37416800, 2023). "GPT gene encodes glutamate pyruvate transaminase, which might be involved in processes related to obesity." (PMID 36046822, 2022). "ASV3566, which corresponds to Eubacterium coprostanoligenes, was correlated with GPR120 and obesity-related markers such as glutamic pyruvic transaminase (GPT) and serum triglyceride (TG)." (PMID 36687627, 2022). "The high fat diet itself induces a significant increase in both GOT and GPT levels which induces obesity and a fatty liver." (PMID 33440605, 2021). "Obesity, serum glutamic-oxalocetic transaminase, serum glutamic pyruvic transaminase, controlled attenuation parameter score, and glycated hemoglobin emerged as significant risk factors in multivariate logistic regression." (PMID 32202504, 2020). "Hepatic fat deposits, liver and serum levels of TG and TC, oxidized hepatic lipids, and hepatic GOT and GPT levels in mice fed on the HFD showed metabolic features similar to human obesity." (PMID 30881473, 2019). "Furthermore, we also presented time serial changes for obesity and diabetic parameters such as BMI, blood glucose, serum GPT enzyme activity, and CSNK2A1 gene and protein expression in this study." (PMID 31929734, 2020). "Our statistical approaches demonstrate that besides the GOT and GPT levels, disorders of lipid metabolism, and obesity, certain other factors, such as demographic characteristics, clinical parameters, and different comorbidities may be critical determinants of survival as well." (PMID 40507868, 2025). "In another integrative methylome–transcriptome analysis, seven key genes were identified—CCRL2, GPT, LGALS12, PC, SLC27A2, SLC4A4, and TTC36—that were hypermethylated in obesity and concurrently showed reduced expression." (PMID 41303351, 2025). "In our study, serum levels of liver function markers such as ASAT/GOT, ALAT/GPT, GGT, and alkaline phosphatase (ALP) were significantly higher in female patients with obesity compared to the control group." (PMID 40463745, 2025). "The highest tertile group was the highest for age, men’s proportion, incidence of smoking and alcohol drinking, blood pressure, heart rate, FPG, TC, TG, LDL, TBA, GPT, GOT, serum UA, and values of obesity indices." (PMID 37029402, 2023). "In summary, we successfully identified seven key genes, namely, CCRL2, GPT, LGALS12, PC, SLC27A2, SLC4A4, and TTC36, which are involved in obesity occurrence and development likely through the immune microenvironment." (PMID 36313453, 2022). "We measured body weight, food intake, plasma glucose and lipids, levels of ALT (GPT) and AST (GOT) for liver function, and serum level of adiponectin, a marker for obesity and obesity-mediated metabolic syndrome." (PMID 33440605, 2021). "We applied various machine learning techniques to visualize and investigate predictive variables leading to metabolic syndrome, which revealed that obesity, serum GOT, serum GPT, CAP score, and HbA1c are the most important predictive variables." (PMID 32202504, 2020). "We found that CAP score, obesity, and HbA1c were the principal factors predicting metabolic syndrome, although E score, γ-GT, LDL, and GPT also considerably affected the predictions." (PMID 32202504, 2020). "Phloretin significantly reduced the serum levels of GOT and GPT, recovering liver function in mice with HFD-induced obesity." (PMID 33014333, 2020). "Obesity involves the recruitment of macrophages according to lipid accumulation in the liver and increases in levels of hepatic enzymes such as GPT/ALT and GOP/AST during the progression of an inflammatory reaction (i.e., NASH)." (PMID 30008738, 2018).